TNFSF13 (TNF superfamily member 13)
Description:
Cytokine that binds to TNFRSF13B/TACI and to TNFRSF17/BCMA. Plays a role in the regulation of tumor cell growth. May be involved in monocyte/macrophage-mediated immunological processes.
Synonyms: APRIL; TALL-2; TRDL-1; CD256; TALL2; ZTNF2; UNQ383/PRO715; TNLG7B
Tractability: Small molecule: a structure with a bound ligand is known. Antibody: a drug acting on it is in phase 2 or 3 trials; UniProt places it where antibodies can reach, with high confidence; its Gene Ontology location is reachable by antibodies, with high confidence. PROTAC: ubiquitination databases record sites on it. Other modalities: a drug acting on it is in phase 2 or 3 trials.
Target class: Secreted protein
Gene: Protein-coding gene on chromosome 17 (7,558,292 to 7,561,608, forward strand). Ensembl gene ENSG00000161955.
Subcellular location: Secreted
Pathways (Reactome):
Immune System: TNFs bind their physiological receptors
Metabolism of RNA: HuR (ELAVL1) binds and stabilizes mRNA
Gene Ontology:
Molecular function: protein binding; cytokine activity; signaling receptor binding; tumor necrosis factor receptor binding
Biological process: positive regulation of isotype switching to IgA isotypes; immune response; lymphocyte homeostasis; positive regulation of B cell proliferation; positive regulation of cell population proliferation; signal transduction; cell communication; signaling
Cellular component: cytoplasm; extracellular exosome; cytosol; extracellular region; nucleoplasm; membrane
Genetic constraint (gnomAD): Loss-of-function variants: 18 observed, 31.33 expected, observed/expected ratio (o/e) 0.57, 90% interval 0.4 to 0.85. The upper end of that interval is the gene's LOEUF score, 0.85, which puts it in group 3 of 6, group 1 being the genes least tolerant of losing a copy. Missense variants: 286 observed, 318.55 expected, observed/expected ratio (o/e) 0.9, 90% interval 0.81 to 0.99. Synonymous variants: 116 observed, 127.29 expected, observed/expected ratio (o/e) 0.91, 90% interval 0.78 to 1.06.
Gene-disease validity (ClinGen):
ClinGen rates the evidence that TNFSF13 causes each of these diseases.
common variable immunodeficiency (autosomal recessive): Limited.
Homologues: Orthologues: chimpanzee TNFSF13 (99% identical), rabbit TNFSF13 (86% identical), dog TNFSF13 (86% identical), pig TNFSF13 (84% identical), guinea pig TNFSF13 (82% identical), mouse Tnfsf13 (80% identical), rat Tnfsf13 (77% identical). Paralogues in human: TNFSF13B (23% identical), TNFSF12 (11% identical).
Diseases named in the same sentence as TNFSF13 in open-access papers:
TNFSF13 is named in the same sentence as 91 diseases in open-access papers, as found by Europe PMC text mining. Sharing a sentence is not in itself a finding about the gene and the disease. The quoted sentences say what the papers report.
COVID-19 (9 papers, 2021 to 2024). A disease caused by infection with severe acute respiratory syndrome coronavirus 2. "Remarkably, although elevated, the levels of APRIL/TNFSF13, sCD30, sCD163, sTNF-R1, and sTNF-R2 were lower in COVID-19 than in pandemic influenza A(H1N1) patients." (PMID 33995342, 2021). "A computational analysis predicted that DC produce IL-18, TNF superfamily member 13 (TNFSF13) and TNFSF13B to promote B and T cell proliferation in early COVID-19 recovery." (PMID 33498725, 2021). "Similarly, in the trajectory signature for alveolar macrophages from mild COVID-19 patients, CALR, MARCO and TNFSF13 followed the expression patterns of CD68 and PSMB8." (PMID 34225749, 2021). "Furthermore, we found low levels of IL-2 and APRIL/TNFSF13 (two immune mediators crucial for T-cell and plasma cell survival), as well as sCD30 (a marker of lymphocyte activation) in the circulation of COVID-19 but not pandemic influenza A(H1N1) patients." (PMID 33995342, 2021).
breast carcinoma (7 papers, 2013 to 2024). "Besides, existing researches have clarified that the overexpression of TNFSF13 associates with more severe classification and worse prognosis in diverse cancers, including breast cancer, multiple myeloma, non-small-cell lung cancer, and pancreatic cancer." (PMID 34712225, 2021). "In breast cancer, TNFSF13 expression is associated with breast cancer classification." (PMID 34712225, 2021). "In one study, it was shown that the endogenous expression of TNFSF13 in a group of TN breast cancer cell lines was strongly correlated with the concentrations of paclitaxel and doxorubicin." (PMID 36430403, 2022). "The clinical significance of TNFSF13 in several cancers was previously analyzed such as NSCLC, breast cancer, leukemia, and other tumor types." (PMID 34923982, 2021).
IgA nephropathy (6 papers, 2019 to 2025). "TNFSF8/TNFSF15 and TNFSF13 loci are also associated with the risk of IgA nephropathy, while TNFSF4/TNFSF18 locus has previously been associated with the risk of eczema, asthma and narcolepsy, all with concordant effects to IgA levels." (PMID 36369178, 2022). "The rs3803800AA genotype of TNFSF13 was also found to be associated with susceptibility to IgA nephropathy (IgAN) and with higher serum IgA levels in comparison to GG and GA genotypes, but not with APRIL serum levels." (PMID 33036273, 2020). "It will be interesting to examine in the future, if CLL patients with the TNFSF13 rs3803800AA genotype are more prone to develop IgA nephropathy." (PMID 33036273, 2020). "Further research is needed to clarify mechanisms by which TNFSF13 affects the recurrence of IgA nephropathy." (PMID 30704417, 2019).
multiple myeloma (6 papers, 2014 to 2024). "The APRIL signaling pathway was active between monocytes and neutrophils (TNFSF13), with its receptor (TNFRSF13B) in high-risk UPPRS myeloma cells." (PMID 37047654, 2023). "We report a set of PB EV-proteins (PDIA3, C4BPA, BTN1A1, and TNFSF13) with a new biomarker potential for myeloma patient outcomes." (PMID 35800053, 2022). "In multiple myeloma (MM), TNFSF13 facilitates MM cell survival by increasing regulatory B cells and T cells via TACI in bone marrow microenvironment." (PMID 34712225, 2021). "TNFSF13 promoted multiple myeloma cell survival through its actions on Breg and Treg cells." (PMID 38590952, 2024). "The tumor necrosis factor ligand superfamily member 13 or APRIL (TNFSF13) and TNFSF12-TNFSF13 were significantly upregulated in EV from MGUS patients when compared to myeloma patient EV." (PMID 35800053, 2022). "Elevated serum levels of TNFSF13 have been reported in oral cavity cancers, and are correlated with increased serum TNF levels, angiogenesis and poor prognosis in multiple myeloma." (PMID 25120605, 2014).
autoimmune disease (5 papers, 2016 to 2025). A disorder resulting from loss of function or tissue destruction of an organ or multiple organs, arising from humoral or cellular immune responses of the individual to their own tissue constituents. "TNFSF13, a tumor necrosis factor, plays a significant role in tumor development and autoimmune diseases, and hypoxia promotes the retention of the intron of TNFSF13 and suppresses the spliced isoform in MCF7 cells, which may contribute to a tumor suppressor effect." (PMID 34722250, 2021). "The cytokine APRIL/TNFSF13, from the TNF superfamily, is a proliferation ligand known to be involved in autoimmune diseases including RA." (PMID 40151315, 2025). "Furthermore, TNFSF13 is also among those genes with the highest concordance, and it encodes APRIL (“a proliferation-inducing ligand”), a member of the TNF ligand superfamily, that is thought to play a role in autoimmune disease and suppresses allergic lung inflammation in mice." (PMID 37206955, 2021). "The downregulation of TNFSF13 in ONFH cartilage may be the reason for corticosteroid-induced ONFH, and most patients with this condition experienced autoimmune diseases in the past and required long-term glucocorticoid treatment." (PMID 39253583, 2024).
glioma (5 papers, 2018 to 2022). A benign or malignant brain and spinal cord tumor that arises from glial cells (astrocytes, oligodendrocytes, ependymal cells). "Our analyses demonstrated the relevance between TNFSF13 and glioma progress and indicated the potential of TNFSF13 as a novel diagnostic onco-inflammatory biomarker and immunotherapy target of gliomas." (PMID 34712225, 2021). "In consideration of the relevance between TNFSF13 and the inflammatory response in gliomas revealed by our analysis, we subsequently investigated seven inflammatory activity signatures to clarify the function of TNFSF13 in the inflammatory response." (PMID 34712225, 2021). "Subsequently, we evaluated the prognostic value of TNFSF13 expression in human gliomas by Kaplan-Meier analysis." (PMID 34712225, 2021). "Given recent studies that showed a vital function of combination therapy with inhibiting immune checkpoints, we performed a correlation analysis of several well-known immune checkpoint molecules to assess the relationship between TNFSF13 and them in gliomas." (PMID 34712225, 2021). "To further evaluate the relevance between TNFSF13 and immune infiltrating, we performed scRNA-seq analysis to investigate the TNFSF13 expression level in different cell clusters in gliomas." (PMID 34712225, 2021). "As shown from TCGA dataset, TNFSF13 was surprisingly upregulated in CL and ME subtypes contrasted with other subtypes among pan-glioma cases, as well as GBM cases." (PMID 34712225, 2021). "Taken together, our elaborate bioinformatics analyses illuminated a potential influence of TNFSF13 in the progression and targeted anticancer treatment for human gliomas." (PMID 34712225, 2021). "Further in vivo and in vitro researches on the regulatory mechanism of TNFSF13 for immunoregulation and tumor microenvironment in gliomas are expected." (PMID 34712225, 2021). "These still further testified that TNFSF13 expression was positively related to M2 macrophages and the progression of glioma." (PMID 34712225, 2021). "TNFSF13 overexpression was particularly relevant to a high degree of gliomas malignancy and more severe prognosis in glioma cases." (PMID 34712225, 2021). "Our analyses initially indicated that TNFSF13 expression level was greatly upregulated in high-grade gliomas based on 2016 WHO classification, especially in IDH-wildtype status GBM." (PMID 34712225, 2021). "Referred to existing researches, our analysis indicated that complicated ligand-receptor interactions worked within tumor microenvironment to regulate glioma malignancy and patient outcome, and expression of those factors was highly relevant to TNFSF13." (PMID 34712225, 2021). "We also confirmed the positive correlation between TNFSF13 and infiltrating immune and stromal cells in glioma microenvironment." (PMID 34712225, 2021). "The images revealed an enhanced expression of TNFSF13 in the increase of pathological grades of glioma samples." (PMID 34712225, 2021). "Furthermore, TNFSF13 plays a crucial role in triple-negative breast cancer, laryngeal squamous cell carcinoma, gastric cancer, and glioma." (PMID 36186454, 2022). "To explore and confirm the role of TNFSF13 in promoting the progression of gliomas, we performed several analyses via public available databases, and the corresponding glioma patient samples with TNFSF13 expression data were collected from TCGA and CGGA datasets." (PMID 34712225, 2021). "In high TNFSF13 gliomas, somatic mutation was proved to correlate with amplification of EGFR and deletion of CDKN2A; while mutation of IDH1 was more frequently observed in low TNFSF13 group." (PMID 34712225, 2021). "These were further evidence that TNFSF13 expression associated with immune response in gliomas, probably in a negative way." (PMID 34712225, 2021).
glioma (continued). "In view of the contribution from genomic alternations and heterogeneity to tumor progression, tumor microenvironment transformation, and drug tolerance, we supposed our analysis provided evidence for the relevance between TNFSF13 overexpression and degree of malignancy in gliomas." (PMID 34712225, 2021). "Moreover, TNFSF13 was remarkably upregulated in CL and ME subtypes compared with other subtypes among gliomas, which immune checkpoint inhibitors and immunosuppressive cytokines were enriched in ME subtype to facilitate immunosuppression and tumor invasion." (PMID 34712225, 2021). "Expectedly, the area under the curve (AUC) were 79.8% in TCGA dataset and 69.2% in CGGA dataset, which suggested that TNFSF13 might be a potential biomarker in the developing progress of glioma." (PMID 34712225, 2021). "Based on TCGA and CGGA datasets, analysis of pan-glioma cohorts revealed that patients with higher expression of TNFSF13 exhibited dramatically poorer overall survival (OS) than patients with lower expression of TNFSF13, and similar correlations were noticed in LGG and GBM cohorts." (PMID 34712225, 2021). "Furthermore, the area under the curve (AUC) of TNFSF13 was 84.1% in pan-glioma cohort and 69.0% in GBM cohort." (PMID 34712225, 2021). "In conclusion, these results demonstrated that TNFSF13 might be a predictive biomarker for more aggressive tumor subtypes and play a crucial part in the progression of glioma." (PMID 34712225, 2021). "Noteworthily, GO and KEGG enrichment analysis for those particular regulons mightily suggested the pertinence between these transcription factors and glioma malignancy, while TNFSF13 expression also correlated with regulon distribution." (PMID 34712225, 2021). "Considering that the molecular features of TNFSF13 in gliomas still remain unclear, we performed large-scale and integrated bioinformatic analyses to characterize TNFSF13 in gliomas." (PMID 34712225, 2021). "Furthermore, single-cell RNA analysis was conducted to dig more potential pertinence of TNFSF13 in TAMs-related immunity and glioma deteriorate." (PMID 34712225, 2021). "Accordingly, TNFSF13 might contribute to the inhibition of T-cell based antitumor immune processes in gliomas." (PMID 34712225, 2021). "Moreover, Receiver operating characteristic (ROC) curve was used to assess the sensitivity and specificity of TNFSF13 expression to distinguish IDH wild-type gliomas from normal tissue." (PMID 34712225, 2021). "ROC curve (AUC>=0.872 in TCGA, AUC>=0.771 in CGGA) further revealed that expression of TNFSF13 might be an idea predictor for the survival outcome of glioma patients." (PMID 34712225, 2021). "Consequently, the expression of TNFSF13 was relevant to worse prognosis in glioma patients." (PMID 34712225, 2021). "Our results suggested that TNFSF13 expression was upregulated in GBM and associated with immunosuppression, which supported the claim that TNFSF13 could be a potential diagnostic marker and treatment target in the clinical management of glioma patients." (PMID 34712225, 2021). "Here, we performed bioinformatic analyses for TNFSF13 (also known as APRIL), a proliferation-inducing ligand of the tumor necrosis factor (TNF) superfamily, aiming to assess its potential for predicting glioma patient’s prognosis and targeted therapy." (PMID 34712225, 2021). "Additionally, higher TNFSF13 expression was relevant to worse progression-free survival (PFS) and disease-specific survival (DSS) in pan-gliomas, LGG, and GBM cohorts." (PMID 34712225, 2021). "Based on TCGA and CGGA datasets, we observed a high and positive correlation between TNFSF13 and PDCD1LG2, HAVCR2, CTLA4, and other checkpoint molecules in pan-gliomas, LGG and GBM analysis, and TNFSF13 expression is tightly correlated with HAVCR2 in glioblastomas." (PMID 34712225, 2021).
glioma (continued). "To further explore particular cell categories related to TNFSF13 expression in tumor microenvironment, we performed a cell enrichment analysis to evaluate the correlation between TNFSF13 and 28 specific infiltrating cell types based on TCGA and CGGA pan-glioma datasets." (PMID 34712225, 2021). "Consequently, TNFSF13 expression was identified positively correlated with interferon, STAT1, MHC-I, MHC-II, HCK, and LCK, while negatively relevant to IgG metagene in pan-glioma analysis and GBM alone analysis in both TCGA and CGGA databases." (PMID 34712225, 2021).
systemic lupus erythematosus (5 papers, 2012 to 2022). An autoimmune multi-organ disease typically associated with vasculopathy and autoantibody production. "Moreover, there are also GWAS reporting the impact of TNFSF13 gene on systemic lupus erythematosus (SLE) and Celiac Disease susceptibility." (PMID 23118916, 2012).
inflammatory bowel disease (3 papers, 2021 to 2026). A spectrum of small and large bowel inflammatory diseases of unknown etiology. "TNFSF13 is a cytokine important for B cell maturation and function, but roles for epithelial TNFSF13 and putative contribution to inflammatory bowel disease are poorly understood." (PMID 41919502, 2026). "Genome-wide association studies (GWASs) in IgAN support that galactose-deficient IgA1 (Gd-IgA1) is heritable, and they also suggest that some GWAS loci, such as CARD9, TNFSF13, and PSMB8, are shared among IgAN, inflammatory bowel disease (IBD), and bacterial infections." (PMID 33436510, 2021).
leukemia (3 papers, 2020 to 2025). A malignant (clonal) hematologic disorder, involving hematopoietic stem cells and characterized by the presence of primitive or atypical myeloid or lymphoid cells in the bone marrow and the blood. "Similarly, several genes adjacent to DMRs in our dataset represent canine homologs of human cancer-associated genes: TNFSF13 is known to be related to tumor cell proliferation in human studies, while RUNXs and MPZL2 are associated with leukemia in human." (PMID 41468414, 2025). "It was reported that TNFSF13 could support leukemia cell proliferation in an NF-κB-dependent manner by binding TNFRSF17 and suppressed apoptosis." (PMID 33215029, 2020).
melanoma (3 papers, 2022 to 2024). A malignant, usually aggressive tumor composed of atypical, neoplastic melanocytes. "BRAF mutated patients had significantly higher expression of APRIL/TNFSF13 and CXCL10 in comparison to BRAF wild-type patients, while NRAS wild-type patients had higher expression of TNFSF13 in comparison to patients with melanomas harboring NRAS mutations." (PMID 37435077, 2023). "In an exploratory fashion, we further studied melanomas from 5 patients with coordinately elevated serum levels of TNFSF13 and CXCL10 or CXCL13." (PMID 37435077, 2023). "APRIL/TNFSF13 is expressed by macrophages, lymphoid cells, as well as tumor cells and keratinocytes, and interestingly, expression of APRIL/TNFSF13 is commonly downregulated in progressive melanomas when compared to normal skin tissue." (PMID 37435077, 2023). "Together these data suggest that 3-component index that integrates high expression of APRIL/TNFSF13, CXCL10, and CXCL13 transcripts in tumor are associated with superior melanoma patients' survival and a pro-inflammatory TME supportive of LA and /or TLS." (PMID 37435077, 2023). "Firstly, we compared the expression levels of 43 immune-stimulator genes between FGFR Mut and FGFR Wt melanoma, with the majority of genes expressing higher in FGFR Mut melanoma, especially ICOSLG and TNFSF13 (P < 0.05)." (PMID 36426352, 2022). "Hence, this small pilot study supports a paradigm for studying expression of a 3 TLS-kine index (APRIL/TNFSF13, CXCL10 and CXCL13) in serum that may predictive presence of histologically defined LA and/or TLS in the TME of melanoma patients." (PMID 37435077, 2023).
bronchiectasis (2 papers, 2020 to 2021). Segmental, irreversible dilation of the bronchial tree resulting in the accumulation of secretions which leads to obstruction. "A recent study identified different inflammation profiles when comparing gingival tissues of bronchiectasis patients having chronic periodontitis, with 7 genes significantly altered in bronchiectasis patients (LTA, LTB, TNFSF4, TNFSF11, TNFSF13, TNFSF13B, and TNFRSF11B)." (PMID 34765263, 2021).